LIF (LIF interleukin 6 family cytokine)
Diseases named in the same sentence as LIF in open-access papers (continued):
Sharing a sentence is not in itself a finding about the gene and the disease.
teratoma (10 papers, 2009 to 2021). A non-seminomatous germ cell tumor characterized by the presence of various tissues which correspond to the different germinal layers (endoderm, mesoderm, and ectoderm). "When LIF was removed and the mESCs were cultured for an additional 24 h, teratomas were still observed in all (4/4) mice injected." (PMID 29137597, 2017). "Teratomas arose from both LIF treated and untreated ES cells, and the resulting teratomas exhibited similar transcriptomes." (PMID 23637952, 2013). "Mouse ESCs maintained under serum-free conditions supplemented with LIF, Bmp4, N2 and B27 are pluripotent and can contribute to the germline in chimeric animals, and grew into teratomas." (PMID 21731714, 2011). "As expected, teratomas were formed when the mESCs on the rigid substrate with LIF were transplanted." (PMID 21179449, 2010). "Additionally, we performed the teratoma formation assay using cells dissociated from the DRG explants cultured for 6 days in the presence of LIF/BMP2/FGF2, and found that teratomas were formed by injecting dissociated DRG cells treated with LIF/BMP2/FGF2." (PMID 28373172, 2017). "It will be interesting in future to determine whether sites at which either Activin/Nodal/Fgf or LIF/BMP signalling is naturally present coincide with sites at which teratomas spontaneously arise in mice and humans." (PMID 26453549, 2015). "When mESCs on the soft gel with LIF were transplanted to NOD-SCID mice subcutaneously for 6 weeks, they grew into a well-developed teratoma (dashed-circles) with cell types of three germ layers." (PMID 21179449, 2010). "They did not differentiate in response to LIF withdrawal when compared to the wild type ES cells and were defective for lineage commitment upon teratoma formation in vivo." (PMID 33624208, 2021). "E14 mouse ESCs cultured on HFF without exogenous LIF for 16 passages were injected intramuscularly into the SCID-beige mice to test their ability to form teratomas, which is one of the standard tests for the pluripotent developmental potential of ESCs in vivo." (PMID 22849865, 2012). "Interestingly, however, when cRGDfC was added to mESCs cultured in the presence of LIF for 24 h and then injected into mice, no teratomas (0/4) were observed but one mouse (1/4) did present with a growth containing mainly fat tissue." (PMID 29137597, 2017).
experimental autoimmune encephalomyelitis (9 papers, 2012 to 2025). An autoimmune demyelinating disease of the central nervous system that is produced experimentally in animals by the injection of homogenized brain or spinal cord in Freund's adjuvant. "This study aimed at evaluating the effects of co-overexpressing beta interferon (IFN-β) and Leukemia inhibitory factor (LIF) in human adipose-derived stem cells (IFN-β/LIF-hADSCs) on the experimental autoimmune encephalomyelitis (EAE)." (PMID 36284106, 2022). "LIF has been found to suppress T-helper 17 cells in an experimental autoimmune encephalomyelitis mouse model and promote Treg proliferation in an MSC-mixed lymphocyte co-culture." (PMID 32188006, 2020). "Using a bacterial artificial chromosome (BAC), we constructed an HSV-1(17+)-based replicative vector deleted of the neurovirulence gene γ134.5, and expressing leukemia inhibitory factor (LIF) as a transgene for treatment of experimental autoimmune encephalomyelitis (EAE)." (PMID 23700462, 2013). "Importantly, the therapeutic administration of both CNTF and LIF has been shown to improve neurological outcome in the murine experimental autoimmune encephalomyelitis (EAE)." (PMID 23077604, 2012). "LIF inhibited Th17 cells differentiation by exerting an opposite effect on STAT3 phosphorylation, which is required for Th17 cell differentiation, in experimental autoimmune encephalomyelitis mice." (PMID 40241721, 2025). "In the murine experimental autoimmune encephalomyelitis (EAE) model, antagonism of LIF and genetic deletion of CNTF worsen disease." (PMID 23077604, 2012). "miPSCs-NPCs exerted the neuroprotective effect via the secretion of LIF leading to a secondary anti-inflammatory role, not due to a cell replacement mechanism in the experimental autoimmune encephalomyelitis (EAE) model." (PMID 38720903, 2024).
nasopharyngeal carcinoma (9 papers, 2014 to 2024). A carcinoma arising from the nasopharyngeal epithelium. "Studies of nasopharyngeal carcinoma have shown that increased cytoplasmic LIF levels are associated with decreased total and phosphorylated YAP." (PMID 35204717, 2022). "High LIF expression in tumor tissue has been associated with poorer overall survival in many cancer types, such as chordomas, oral squamous cell carcinoma, nasopharyngeal carcinoma, pancreatic adenocarcinoma, cervical cancer, and renal cancer." (PMID 35204717, 2022). "Interestingly, high expression of an intracellular LIF mutant was associated with more invasive and aggressive tumors in nasopharyngeal carcinoma." (PMID 34395259, 2021). "In nasopharyngeal carcinoma (NPC) high levels of LIF are associated with higher degrees and radio resistance, tumor progression, and decreased DNA repair." (PMID 34395259, 2021). "Nasopharyngeal carcinoma cells in vitro and xenograft mouse studies were treated with soluble LIF receptors, LIF antagonists (decreases LIF-mediated effects), or mTOR inhibitors, leading to growth arrest and increased sensitivity to gamma radiation." (PMID 38672566, 2024). "Further experiments to determine regulators of radioresistance in nasopharyngeal carcinoma used cell lines to identify MAP2K6 as an important regulator tied to LIF signaling-induced radioresistance." (PMID 35204717, 2022). "The Src/Bcr-Abl tyrosine kinase inhibitor Saracatinib (AZD-0530) has been investigated within nasopharyngeal carcinoma as a treatment for preventing LIF-mediated increased invasiveness." (PMID 35204717, 2022). "Within nasopharyngeal carcinoma cells and xenograft mouse models, increased LIF activates mTORC1/p70S6K signaling that suppresses the normal DNA damage responses that stimulate apoptosis or DNA repair, and thereby induces radioresistance of these tumors." (PMID 35204717, 2022). "During the preparation of this paper, a very recent study reported that exogenous LIF activates the mTOR pathway in nasopharyngeal carcinoma cell lines, which is consistent with our findings." (PMID 24553191, 2014). "High intracellular LIF is correlated with lower metastasis-free and recurrence-free survival in nasopharyngeal carcinoma, in which xenograft zebrafish and mouse models reveal that LIF enhances vascular invasion, invadopodia formation, and focal adhesion kinases via suppression of YAP1." (PMID 35204717, 2022). "Nasopharyngeal carcinoma patients with higher serum levels of LIF were more likely to have local tumor recurrence, and receiver-operating characteristic (ROC) analysis showed a cutoff value of 4.96 pg/mL could differentiate between patients with complete remission and those with recurrence." (PMID 35204717, 2022). "It will be interesting to investigate whether LIF also activates the mTOR pathway through AKT in nasopharyngeal cancer, whether the activation of LIF-AKT-mTOR pathway exists in other types of tumors, and plays an important role in tumorigenesis in future studies." (PMID 24553191, 2014).
pancreatic ductal adenocarcinoma (9 papers, 2021 to 2025). An infiltrating adenocarcinoma that arises from the epithelial cells of the pancreas. "KRAS mutation could induce LIF expression in human pancreatic ductal adenocarcinoma (PDAC) cells, and LIF inhibits the intracellular Hippo pathway and promotes tumorigenesis by facilitating YAP/TAZ-TEAD interaction and up-regulating the expression of the YAP1 target genes CNTF and ANKRAD." (PMID 35740622, 2022). "Systematic proteomic analysis revealed that STAT3 activation and concomitant production of LIF play a promotive role in pancreatic ductal adenocarcinoma development." (PMID 40416597, 2025). "These levels are comparable with the serum LIF levels in some cancer patients, including those with pancreatic ductal adenocarcinoma (PDAC) or oesophageal adenocarcinoma (OAC)." (PMID 38245529, 2024). "CircFARP1 increased leukemia inhibitory factor (LIF) expression through sponging miR-660, which enhanced gemcitabine resistance in pancreatic ductal adenocarcinoma." (PMID 37107669, 2023). "In pancreatic ductal adenocarcinoma cells and mouse models, LIF signaling enhances migration of peripheral nerve schwann cells via STAT3 and AKT pathways." (PMID 35204717, 2022). "Within pancreatic ductal adenocarcinoma, circulating LIF levels correlate to disease status, and to tumor responses to chemotherapeutics." (PMID 35204717, 2022). "The leukemia inhibitory factor (LIF), is a cytokine belonging to IL-6 family, whose overexpression correlate with poor prognosis in cancer patients, including pancreatic ductal adenocarcinoma (PDAC)." (PMID 36998446, 2023). "Among the genes that are upregulated in pancreatic ductal adenocarcinomas (PDAC), the leukaemia inhibitory factor (LIF), a cytokine belonging to IL-6 family, has emerged as potential therapeutic candidate." (PMID 36359879, 2022). "LIF is a key paracrine factor from stromal cells acting on cancer cells; and LIF blockade or genetic LIFR deletion slows tumor progression, and augments the efficacy of chemotherapy to prolong survival of pancreatic ductal adenocarcinoma [PDAC]." (PMID 34400617, 2021).
triple-negative breast carcinoma (9 papers, 2020 to 2024). An invasive breast carcinoma which is negative for expression of estrogen receptor (ER), progesterone receptor (PR), and human epidermal growth factor receptor 2 (HER2). "For triple-negative breast cancer, the enhanced level of LIF accelerates oncogenesis and progression by activating the LIF-STAT3 signaling pathway." (PMID 35654787, 2022). "Our data reveal that the circSEPT9 mediated by E2F1 and EIF4A3 facilitates the carcinogenesis and development of triple-negative breast cancer through circSEPT9/miR-637/LIF axis." (PMID 32264877, 2020). "Additionally, circSEPT9 mediated by E2F1 and EIF4A3 propels the carcinogenesis and progression of triple-negative breast cancer via the circSEPT9/miR-637/LIF axis." (PMID 38956466, 2024). "Similarly, the ELISA results showed that the level of LIF secreted by adipocytes increased significantly, especially in the co-culture group with triple-negative breast cancer MDA-MB-231 and BT549 cell lines." (PMID 35280694, 2022). "For example, circSEPT9 regulated by E2F transcription factor 1 (E2F1) and eukaryotic translation initiation factor 4A3 (EIF4A3) pushes the cancerous derivation of triple-negative breast cancer through the circSEPT9/miR-637/Leukemia Inhibitory Factor (LIF) axis." (PMID 34540684, 2021). "For instance, it was recently found that E2F1 and EIF4A3 might promote the biogenesis of circSEPT9 and the occurrence and development of triple-negative breast cancer by acting on the miR-637/LIF axis." (PMID 33323543, 2020). "The triple negative breast cancer cell line MDA-MB-231 was shown to highly express LIF, and treatment with LIF neutralizing antibodies impeded proliferation." (PMID 34395259, 2021).
diabetes (8 papers, 2012 to 2026). "We identified C4b, CFD, CXCR6, and LIF that were time dependently increased as diabetes progression as non-invasive biomarker candidates for diabetic nephropathy." (PMID 33922243, 2021). "The added value of nanoparticles to deliver immune modulators plus growth factors such as LIF expands the potential of this novel therapeutic approach to cell therapy for diabetes." (PMID 23227162, 2012). "Among subjects with diabetes, those with TIR ≤ 70% had higher levels of IL-1α, IL-1β, IL-6, IL-12 p70, IL-16, LIF, M-CSF, MCP-1, MCP-3, RANTES, TNF-α, TNF-β, and b-NGF, and lower levels of IL-1α, IL-4, IL-10, GM-CSF, and MIF than individuals with TIR > 70%." (PMID 37893217, 2023). "In conclusion, our study provides transcriptomic data of an animal model with progressive diabetes-induced nephrotoxicity, and also demonstrates that C4b, CXCR6, CFD, and LIF are specific and sensitive biomarkers for early detection of diabetic nephropathy." (PMID 33922243, 2021). "Aberrant expression of both LIF and VEGFA has been previously reported in the context of diabetes." (PMID 33062917, 2020). "There have been studies assessing the expression of LIF and VEGFA as implantation modulators; however, the expression changes of these molecules in diabetic conditions and the effects of diabetes treatment drugs on the endometrial expression of these molecules have not been well-understood." (PMID 33062917, 2020). "However, endometrial LIF and VEGFA expressions modulation during implantation in the context of diabetes is not well-understood." (PMID 33062917, 2020).
myocardial infarction (8 papers, 2016 to 2025). Gross necrosis of the myocardium, as a result of interruption of the blood supply to the area, as in coronary thrombosis. "In this model the myocardial infarction-associated muscle wasting was recovered upon interval exercise and LIF was upregulated as well in gastrocnemii." (PMID 30984014, 2019). "Berry MF, using an adenovirus to overexpress the LIF gene in a rat myocardial infarction model, found that rats overexpressing LIF had more surviving myocardium and less fibrosis, suggesting a cardioprotective effect of LIF binding to its receptor." (PMID 39726944, 2024). "Targeted overexpression of LIF in rats on myocardial infarction exerted protection by preserving the myocardium and reducing fibrosis." (PMID 35163735, 2022). "In a murine model of myocardial infarction, intramuscular injection of LIF cDNA enhanced cardiomyocyte survival and cardiac regeneration." (PMID 35163735, 2022). "The transplantation of skeletal muscle pericytes in a model of acute myocardial infarction improved cardiac function by reducing hypoxia and increasing angiogenesis due to increased expression of molecules such as IL-6 and LIF." (PMID 32923442, 2020). "A recent study showed the effect on muscle expression of an IL-6-like cytokine, LIF, in rats undergoing myocardial infarction." (PMID 30984014, 2019). "We have previously reported that leukemia inhibitory factor (LIF) attenuates cardiac remodeling after myocardial infarction (MI) through anti-apoptotic and angiogenic effects." (PMID 27227407, 2016). "Oncostatin M (OSM) and leukemia inhibitory factor (LIF) signaling protects the heart after myocardial infarction (MI)." (PMID 35008777, 2021). "As the ligand for LIF, LIFR expression may be significantly upregulated in certain stress or disease states, such as myocardial infarction, as a protective and reparative mechanism of the body." (PMID 39726944, 2024). "Furthermore, a sharp decrease in serum LIF was noticed in mice after myocardial infarction (MI)." (PMID 37103052, 2023).
asthma (7 papers, 2012 to 2025). "Mounting evidence suggests that LIF is associated with the development of asthma, LIF might function as a proinflammatory cytokine in the airways by augmenting eosinophil recruitment and activation." (PMID 40496853, 2025). "Regarding the lung, several studies have investigated LIF's role in the pathophysiology of different lung diseases, such as acute respiratory distress syndrome, asthma, chronic airway inflammation and inflammation induced by tobacco." (PMID 22291973, 2012). "Epithelial damage correlates with airway hyperreactivity in asthma patients and the increased protein levels in the BALF of animals treated with anti-LIF IgG prior to RSV infection could also contribute to the enhanced airway resistance observed in these animals." (PMID 25277705, 2014).
endometrial cancer (7 papers, 2020 to 2024). Primary or metastatic malignant neoplasm involving the endometrium (mucous membrane that lines the endometrial cavity). "Certain signaling pathways were differentially targeted by miR-146a-5p in various cancers, including LIF-Stat3 when reported in the endometrium of patients with implantation failure, NOTCH 1/2 in endometrial carcinoma, and the EGFR, NF-κB, TGF-β, and SMAD4 pathways in other tumor types." (PMID 37240034, 2023).
Insulin resistance (7 papers, 2011 to 2025). Increased resistance towards insulin, that is, diminished effectiveness of insulin in reducing blood glucose levels. "IL-6, IL-11, OSM, and LIF enhance acute-phase liver responses, cause insulin resistance in liver cells, and drive macrophages to a pro-inflammatory M1 state, thus worsening liver inflammation." (PMID 40969371, 2025). "Chronic LIF exposure in cardiomyocytes was linked to insulin resistance, however the role of LIF in induction of IR in adipose tissue is not known." (PMID 21978410, 2011). "Nonetheless, the overexpression of LIF in adipose tissue has been observed to reduce hepatic steatosis and insulin resistance, thereby slowing the progression of MAFLD." (PMID 40969371, 2025). "Both the GTT and the ITT revealed a worsening of body glucose handling, which suggests that OR mice under hypothalamic LIF inhibition develop systemic insulin resistance." (PMID 28865476, 2017). "At least in part, the deterioration in glucose tolerance in OR mice treated with the anti-LIF antibody was due to the development of insulin resistance, as determined by an insulin-tolerance test and the determination of the constant for glucose decay during the insulin tolerance test (kITT)." (PMID 28865476, 2017).
rheumatoid arthritis (7 papers, 2008 to 2025). A chronic, systemic autoimmune disorder characterized by inflammation in the synovial membranes and articular surfaces. "Gadient and Patterson reported that, in addition to the systemic acute phase reaction, IL-6 and LIF are associated with several acute and chronic inflammatory diseases, including rheumatoid arthritis and bacterial meningitis." (PMID 31940845, 2020). "Furthermore, it has been reported that LIF is chemotactic for inflammatory cells and stimulates pro-inflammatory cytokines in various inflammatory disorders such as rheumatoid arthritis, cutaneous inflammation, and nervous system injury." (PMID 27227407, 2016). "TNF-α, IL-6 and LIF also contribute to tissue erosion in advanced stages of OA, although their implication in rheumatoid arthritis (RA) prevails." (PMID 22051322, 2011). "In pathology, LIF released by inflamed synovium contributes to cartilage destruction by altering MMP production, and is likely to induce osteoclastic bone erosions in rheumatoid arthritis." (PMID 23533592, 2013). "The aims of this study were to do, comparative analysis of the levels of different cytokines such as LIF, TNF-alpha, IL-1, IL-6 and OSM, in the synovial fluid samples aspirated from 10 Rheumatoid arthritis (RA), 25 Osteoarthritis (OA) and 7 Mixed arthropathies (MA) patients." (PMID 21593968, 2008).
Arthritis (6 papers, 2005 to 2024). Inflammation of a joint. "The IL-6 family cytokines LIF and IL-11 are also implicated in arthritis." (PMID 33374841, 2020). "Eventually, LIF is also overexpressed in arthritis and suppresses proteoglycan synthesis." (PMID 39202038, 2024). "Apart from TGF-β, LIF can also be induced by IL-1β during arthritis, which could account for these differences." (PMID 36850003, 2023). "The levels of IL-3, IL-5, IL-9, and LIF, as well as those of GM-CSF and VEGF, did not increase in the setting of CFA-induced arthritis." (PMID 36293292, 2022).